SNORA21 (small nucleolar RNA, H/ACA box 21)
Synonyms: ACA21
Gene: Small nucleolar RNA gene on chromosome 17 (38,852,863 to 38,852,994, reverse strand). Ensembl gene ENSG00000199293.
Gene Ontology:
Biological process: RNA processing
Cellular component: nucleolus
Homologues: Orthologues: chimpanzee SNORA21 (100% identical), macaque SNORA21 (99% identical), rat Snora21 (90% identical), dog SNORA21 (89% identical), mouse Snora21 (89% identical), pig SNORA21 (85% identical), guinea pig SNORA21 (84% identical). Paralogues in human: SNORA21B (63% identical).
Diseases named in the same sentence as SNORA21 in open-access papers:
SNORA21 is named in the same sentence as 9 diseases in open-access papers, as found by Europe PMC text mining. Sharing a sentence is not in itself a finding about the gene and the disease. The quoted sentences say what the papers report.
ameloblastoma (2 papers, 2017 to 2021). The most common odontogenic tumor, arising from the epithelial component of the embryonic tooth and usually affecting the molar-ramus region of the mandible or maxilla. "Further validation in an independent cohort points out the long non-coding (lncRNAs) and small nucleolar RNA (snoRNAs): LINC340, SNORD116-25, SNORA11, SNORA21, SNORA47 and SNORA65 as a distinct ncRNA signature of ameloblastoma." (PMID 27965463, 2017). "We have in this study reported significantly higher expression of a number of snoRNAs (SNORD116-25, SNORA11, SNORA21, SNORA47 and SNORA65) in ameloblastoma." (PMID 27965463, 2017). "Small nucleolar RNAs (snoRNAs) comprise a particular group of noncoding RNAs, which role in odontogenic tumors is still unknown, although the overexpression of SNORD116-25, SNORA11, SNORA21, SNORA47 was previously demonstrated in ameloblastomas." (PMID 33680332, 2021). "The result corroborates that SNORA65, SNORA21, SNORA47, SNORD116-25 and LINC340, which were validated here by RT and qPCR assays, belonged to the top most significantly expressed snoRNAs and lncRNAs in ameloblastoma." (PMID 27965463, 2017).
colorectal cancer (2 papers, 2020 to 2025). A primary or metastatic malignant neoplasm that affects the colon or rectum. "For example, SNORA21 has been identified as a key oncogenic snoRNA in colorectal cancer, where its inhibition results in decreased cell proliferation and invasion through modulation of multiple cancer-related pathways, including the Hippo and Wnt signaling cascades." (PMID 41375049, 2025). "For instance, SNORA21 showed oncogenic properties in human colorectal cancer, and elevated SNORA21 served as an independent factor for predicting poor survival; SNORA42 expression was an independent prognostic factor for overall survival and disease-free survival of colorectal cancer." (PMID 32126023, 2020).
gastric cancer (2 papers, 2022 to 2023). A primary or metastatic malignant neoplasm involving the stomach. "SNORA21 is upregulated in gastric cancer and acts as a novel independent indicator for gastric cancer prognosis." (PMID 35821006, 2022).
lung carcinoma (2 papers, 2017 to 2024). "Ten of these ncRNAs (miRs-93-5p, 103a-3p, 126-3p, 146b-5p, 205-5p, 944, 1254, and 1285-3p, and snoRA21 and snoRA80) showed increased expression, whereas two ncRNAs (miR-4251 and snoRA3) had decreased expression in WA patients with lung cancer when compared with cancer-free AA smokers." (PMID 39540714, 2024). "SNORA65 overexpression in metastasised oral squamous cell carcinoma (OSCC), SNORA21 and SNORA47 in lung cancer were also reported previously." (PMID 27965463, 2017). "Interestingly, SNORA65 has been correlated with metastasization in OSCC, SNORA21 and SNORA47 with lung cancer." (PMID 27965463, 2017).
non-small cell lung carcinoma (2 papers, 2017 to 2021). A group of at least three distinct histological types of lung cancer, including non-small cell squamous cell carcinoma, adenocarcinoma, and large cell carcinoma. "The high expression of SNORA21 and SNORA47 in patients diagnosed with non-small cell lung cancer has been associated with poor overall survival." (PMID 33680332, 2021). "Higher expression of SNORA21 and SNORA47 has earlier been associated to poor overall survival in patients with non-small cell lung cancer." (PMID 27965463, 2017).
cancer (5 papers, 2020 to 2025). A tumor composed of atypical neoplastic, often pleomorphic cells that invade other tissues. "For example, SNORA21 promotes CRC cell proliferation by regulating cancer-associated pathways such as Hippo and Wnt signaling pathways, and overexpression of SNORA21 has been reported to be associated with distant metastasis in CRC." (PMID 36612126, 2022). "Another study showed that SNORA21 can promote CRC cell proliferation by regulating cancer-related pathways such as Hippo signaling pathway and Wnt signaling pathway and so on, and that high levels of SNORA21 is related to distant metastasis in CRC." (PMID 35552378, 2022). "SNORA21 is upregulated in CRC and promotes cancer progression, acting as a key oncogenic snoRNA to enhance cell proliferation and invasion via regulating multiple cancer-related pathways." (PMID 32122355, 2020). "Importantly, this oncogenic activity appears to extend beyond canonical rRNA modification mechanisms, suggesting that SNORA21 influences these signaling cascades through non-traditional functional mechanisms, thereby illustrating the expanding repertoire of snoRNA functions in cancer biology." (PMID 41375049, 2025).
tumor (3 papers, 2017 to 2023). "For example, SNORA21, SNORA24, and SNORA42 are upregulated in CRC and promote tumor growth both in vivo and in vitro; SNORD1C maintains the stemness of CRC cells and resistance to the chemotherapeutic drug 5-FU by activating the Wnt pathway." (PMID 37907779, 2023). "It was found that the accumulated ncRNA levels (LINC340, LINC342, SNORD116-25, SNORA11, SNORA21, SNORA47, SNORA65; r = 0.5789, p-value = 0.0075) had a positive but moderate correlation with tumour size." (PMID 27965463, 2017).
SNORA21 also shares sentences with these, for which no sentence is quoted: odontogenic tumors (1 paper); oral squamous cell carcinoma (1).